MC1R (melanocortin 1 receptor)
Diseases named in the same sentence as MC1R in open-access papers (continued):
Sharing a sentence is not in itself a finding about the gene and the disease.
melanoma (continued). "Furthermore, the epistatic effect of MC1R on CDKN2A accounts for the markedly increased risk of melanoma development in individuals carrying both genetic alterations." (PMID 37239385, 2023). "This may have important biological consequences, as it should help MC1R variant melanocytes and melanoma cells to cope with the oxidative stress resulting from the pheomelanic phenotype associated with their MC1R genotype." (PMID 37762683, 2023). "In addition, individuals with MC1R polymorphism, clinically characterized by red hair/fair skin, have a higher melanoma risk, together with squamous cell and basal carcinoma." (PMID 37239385, 2023). "No variant in the high-penetrance genes studied was found, but two RHC variants of the MC1R gene (R/R) could explain, partly, the high-risk profile for melanoma seen in this proband." (PMID 37958811, 2023). "In transgenic mouse studies, it was shown that increased melanoma risk caused by MC1R inactivation was dependent upon pheomelanin production even in the absence of UV, and this risk was reversed by ablation of all pigmentation (introduction of an albinism mutation)." (PMID 36834954, 2023). "In primary melanomas, we found a strong association between higher MC1R expression and a Breslow’s depth greater than 1 mm (p < 0.0001), presence of ulceration (p = 0.0008), presence of BRAFV600E mutation (p = 0.008), and mucosal melanoma versus non-mucosal melanoma (p = 0.0279)." (PMID 37790306, 2023). "The proband where the POT1 VUS was detected (MH16) also showed two MC1R variants (R/u), fair skin, light hair, a history of sunburn in childhood, a personal history of six primary melanomas and thyroid cancer, and a family history of melanoma." (PMID 37958811, 2023). "However, our previous work showed a significant induction of oxidatively-induced DNA strand break repair downstream of variant MC1R in BRAF-mutated human melanoma cells." (PMID 37762683, 2023). "Therefore, common melanoma-associated MC1R variants display biased signaling and significant genoprotective activity." (PMID 37762683, 2023). "In melanoma, activating/inactivating mutations of GPCRs include melanocortin 1 receptor (MC1R)." (PMID 37240209, 2023). "Our germline variant analysis demonstrated that relatively common MC1R variants associated with red hair and melanoma risk might unexpectedly be protective against the development of multiple cancers." (PMID 37679505, 2023). "Furthermore, one single nucleotide polymorphism of the glutathione S-transferase gene GSTP1 that diminishes the enzyme activity has been correlated with melanoma predisposition, with a synergic effect when co-present with alternative alleles of MC1R." (PMID 35453297, 2022). "MC1R-defective individuals, because of their tendency to be undermelanized, they should accumulate more UV mutagenesis over time and would therefore be at higher risk for melanoma as a result." (PMID 35452484, 2022). "Thus, loss of function of MC1R promotes initiation in a UV-independent manner, demonstrating its tumor suppressor activity and a key role in the initiation of melanoma." (PMID 35158973, 2022). "Importantly, extensive genetic analyses of large cohorts have estimated a 60% increased risk of melanoma for carriers of any MC1R variant, with an additive effect for multiple variants." (PMID 35892921, 2022). "People carrying MC1R variants have a higher tendency to develop melanoma." (PMID 36551302, 2022). "Common DNA variants at the MC1R gene encoding melanocortin one receptor on the melanocytes that produce a melanin pigment have been associated with tanning ability, hair color, and KC and melanoma risk." (PMID 35449187, 2022). "The MC1R gene encoding for the αMSH receptor is a well-characterized melanoma susceptibility gene." (PMID 35892921, 2022).
melanoma (continued). "Since the activity of MC1R is an important regulator of eumelanin synthesis and a determinant of the DNA damage response to UV and the risk of melanoma, the melanocyte cultures used in this study were all tested and found to respond avidly to α-MSH, indicating that they express functional MC1R." (PMID 35740103, 2022). "Individuals who are MC1R carriers are at higher risk of melanoma." (PMID 35884596, 2022). "Notably, we detected an association with the MC1R variant rs1805008 for melanoma (OR [95% CI] = 1.56 [1.35, 1.81], p = 2.73 × 10−9), when comparing all individuals with at least one melanoma diagnosis plus any other cancer diagnosis to cancer-free controls." (PMID 36199081, 2022). "Furthermore, MC1R is a melanoma susceptibility gene, and the loss-of-function variants of MC1R have been found in 26–40% of melanoma patients." (PMID 36551302, 2022). "Interestingly, it was reported that recessive yellow mice, co-expressing loss-of-function MC1R and activating BRAFv600E mutation are characterized by a significantly higher risk to develop a more invasive melanoma compared to albino ones." (PMID 35453297, 2022). "The MC1R germline variation increases the risk of BRAF-mutant melanoma." (PMID 36551302, 2022). "Accordingly, we hypothesized that negative regulators of MC1R functional coupling may also modulate the susceptibility to melanoma and/or the course of the disease." (PMID 35892921, 2022). "RHC MC1R variant carriers develop melanomas with less blotches of pigment." (PMID 34440462, 2021). "We addressed the occurrence of MITF-E318K and its association with germline status of CDKN2A and MC1R genes in a hospital-based series of 248 melanoma patients including cohorts of multiple, familial, pediatric, sporadic and melanoma associated with other tumors." (PMID 34573422, 2021). "We conducted a randomized trial to examine whether providing MC1R genetic risk information together with precision prevention materials would increase primary and secondary melanoma preventive behaviors compared to providing generic prevention materials only." (PMID 34201795, 2021). "Furthermore, regulation of palmitoylation, which has been shown to be reduced in RHC MC1R, has been proven to reduce melanoma risk in in vitro and animal models." (PMID 34356109, 2021). "MC1R r variants are more prevalent in childhood and adolescent melanoma than in adult melanoma." (PMID 34440462, 2021). "The theoretical reduction of melanomas through the “removal” of one of the nine most prevalent MC1R variants (i.e., attributable risk) ranges from 1.2 to 8.9% and approaches 40% when summed across variants; this proportion is 30% and 45% for basal and squamous cell skin cancers, respectively." (PMID 34439206, 2021). "MC1R is a G-protein-coupled receptor, can cause increased pigmentation, G 1-like cell cycle arrest induced by ultraviolet B, and control senescence and melanoma in vivo and in vitro, which plays a central role in the prevention of melanoma." (PMID 33719345, 2021). "Furthermore, germline carriers of the CDKN2A p16-Leiden deletion mutation in a large collection of Dutch families showed an increased risk of melanoma in carriers of MC1R variant alleles, with the R151C allele explaining most of this association." (PMID 34356109, 2021). "The risk conferred by MC1R variants is notably stronger among individuals with phenotypes associated with average to lower melanoma risk, including those with darker natural hair color, those who tan well, do not severely burn, and/or develop fewer freckles after sun exposure." (PMID 34201795, 2021). "In addition, melanoma patients carrying MC1R variants as well as CDKN2A mutations, show clinically hypopigmented nevi and, at RCM, roundish cells infiltrating the dermo–epidermal junction." (PMID 34356109, 2021). "Factors such as UV exposure, allele frequencies and genetic background may contribute to the variation in melanoma risk associated with MC1R." (PMID 34680938, 2021).
melanoma (continued). "MC1R genetic testing may unmask previously unrecognized disease risk, especially among individuals with few melanoma phenotypic risk factors." (PMID 34201795, 2021). "Nonetheless, the inheritance of specific MC1R variants may be a robust marker of increased risk of melanoma and keratinocyte skin cancers." (PMID 34439206, 2021). "Furthermore, MC1R variants have also been related to melanoma occurring in childhood and adolescents." (PMID 34356109, 2021). "MC1R RHC variants have been described in hypopigmented melanomas." (PMID 34440462, 2021). "Furthermore, MC1R variants double the risk of melanoma in CDKN2A mutation carriers, which is three times higher in carriers of the RHC variants." (PMID 34442055, 2021). "Several red hair color variants of MC1R are also associated with increased melanoma risk." (PMID 34001865, 2021). "Additionally, carriers of A148T mutation of CDKN2A in association with non-synonymous MC1R variants (V60L, R151C, R160C and R163Q) have a 2- to 6-fold increased risk of melanoma." (PMID 34356109, 2021). "Interestingly, MC1R r variants were found to be more prevalent in childhood and adolescent melanoma than in adult ones, especially in patients aged 18 years or younger." (PMID 34356109, 2021). "Studies show that some SNPs of MC1R are involved in the occurrence and development of melanoma, so we explored whether MC1R SNPs are associated with CRC." (PMID 34698109, 2021). "Some studies have shown that MC1R expression or its splicing variants could predict unfavorable prognosis in melanoma patients." (PMID 34698109, 2021). "Several RHC-variants of MC1R also associate with increased melanoma risk." (PMID 34001865, 2021). "Conversely, MC1R variants are inversely correlated with BRAF V600K-positive melanomas." (PMID 34442055, 2021). "Overall, MC1R is considered a moderate-risk gene for melanoma development." (PMID 34356093, 2021). "The clinical implications of the impact of germline MC1R variants in melanoma and NMSCs’ risk, together with the additional risk conferred by somatic mutations in other peculiar genes, as well as the role of MC1R screening in skin cancers’ prevention will be addressed in the current review." (PMID 34356109, 2021). "However, some international studies in general population and melanoma family settings have demonstrated a range in the prevalence and variation of MC1R variants according to geographic location." (PMID 32350296, 2020). "However, the most frequent variants in the MC1R gene were highly inactivating and reflected variants associated prevalently with risk of melanoma, photoaging, and with RHC phenotype." (PMID 32605315, 2020). "Similarly, spontaneous melanoma initiation was observed in MC1R-truncated, BRAFV600E-mutated mouse models." (PMID 32850409, 2020). "Multiple studies have demonstrated that MC1R variation confers increased risk for melanoma." (PMID 32429485, 2020). "The melanocortin-1 receptor (MC1R) has been found to be a low-risk melanoma susceptibility gene." (PMID 32605315, 2020). "Moreover, MC1R variants, which influence phototype and are associated with melanoma risk, had a similar distribution in the two study groups, therefore not affecting our analyses." (PMID 32054529, 2020). "Interestingly, it was recently found that the red hair variants of MC1R differentially affected melanoma outcome between men and women, further supporting the gender differences in melanoma arising from a genetic background." (PMID 30871230, 2019). "Melanoma was first diagnosed 24, 39, and 57 days after the final UV irradiation in mice expressing the palmitoylation defective MC1R (MC1RC315S), MC1R RHC variant (MC1RR151C), and MC1RWT respectively, indicating that melanoma incidence was associated with MC1R status." (PMID 30787281, 2019). "In the in vitro study, the high accumulation of 111In-labeled 4-arm DOTA-α-MSH may be caused by the effect of lipophilicity and high affinity for MC1-R in B16-F1 melanoma cells." (PMID 30901323, 2019).
melanoma (continued). "This is in agreement with the fact that human variant alleles of MC1R may increase melanoma risk independently of UV exposure." (PMID 31717496, 2019). "The increased melanoma risk attributable to MC1R RHC variants may arise in part through skin pigmentation since pheomelanin in redheads contributes to melanomagenesis through UV radiation (UVR)-independent oxidative damage." (PMID 30787281, 2019). "Further support for the role of MC1R in determining the extent of UV-induced genotoxicity and mutagenesis came from a recent report that loss-of-function MC1R variants increase the risk of melanocytes to acquire UV signature mutations that promote malignant transformation to melanoma." (PMID 30205559, 2018). "Based on previous reports, α-MSH and MC1R are associated with both melanogenesis and melanoma." (PMID 29397551, 2018). "MC1R, a G‐protein coupled receptor with high affinity for alpha‐melanocyte stimulating hormone (αMSH), modulates pigment production in melanocytes from many species and is associated with human melanoma risk." (PMID 29316344, 2018). "The discrepancies found in this study indicate the variant rs34090186 in the MC1R gene, some variants of which were reported to be related to increased risk of PD and melanoma, may play a risk role in ET, confirming a potential association between ET and PD." (PMID 30252209, 2018). "We have also investigated the possible protective role of oral administration of PL in patients at risk of malignant melanoma (MM) and evaluated the influence of PL in the interaction between MC1R polymorphisms and the cyclin-dependent kinase (CDK) inhibitor 2A gene (CDKN2A) status with MED." (PMID 29998107, 2018). "We therefore hypothesized that this variant, if leading to a constitutive MC1R receptor as seen with the Sombre mutant, could influence melanoma penetrance and worsen the phenotype of animals carrying the MC1R*2 allele." (PMID 29963229, 2018). "As such, MC1R predicts melanoma risk in African-American, Spanish, and Mediterranean populations, with at least one study indicating that MC1R may confer greater risk on individuals with darker skin, compared to those with lighter skin." (PMID 28442450, 2017). "Variants in the melanocortin-1 receptor (MC1R) gene are present in approximately 50% of the population, are major factors in determining sun sensitivity, and confer a 2-to-3-fold increase in melanoma risk in the general population, even in populations with darker skin." (PMID 28442450, 2017). "Importantly, variation in MC1R is associated with melanoma risk after adjustment for hair color and skin type." (PMID 28442450, 2017). "A recent study showed that protein palmitoylation could represent a strategy to rescue the activity of variant MC1R, associated with melanoma development." (PMID 29156643, 2017). "A recent study provided evidence that MC1R contributes to the mutational load in melanoma." (PMID 29156643, 2017). "Other studies have also identifiedseveral MC1R coding variants related to melanoma susceptibility.Understanding the expression and activity regulation of this receptor is essential tocomprehend how it affects melanogenesis and the risk of developing melanoma." (PMID 28486572, 2017). "Thus, the risk of melanoma is polygenetic comprising interactions between MC1R variants, other pigmentory gene variants, dysfunctional DNA repair genes and immuno-inflammatory genes." (PMID 26850723, 2016). "Variants in the MC1R have been studied extensively in relation to the risk of developing various skin cancers, and certain MC1R variants are associated with increased survival of melanoma patients." (PMID 26938746, 2016). "As melanoma susceptibility is often related to the presence of ‘loss‐of‐function’ MC1R variants, the role of the functional MC1R/αMSH in activating DNA repair suggests that melanin/melanogenesis may have several roles that influence skin cancer risk." (PMID 27454804, 2016).
melanoma (continued). "Moreover, inherited variation in the MC1R gene is considered a genetic marker for moderately increased risk of melanoma." (PMID 26863566, 2016). "Even though high melanoma risk alleles clearly exist in e.g. CDKN2A, it is speculated if the melanoma risk might be attributable to combinations of low to moderate risk alleles in e.g. MC1R, TYR, and ASIP." (PMID 26938746, 2016). "In animal model systems, null alleles of Mc1r (Mc1re/e) have been shown to co-operate with BrafV600E to promote melanoma development via mechanisms including enhanced lipid peroxidation, a phenotype rescued on an albino mouse background owing to a lack of pheomelanin production." (PMID 27403562, 2016). "Despite these insights, it is still unclear whether MC1R germline variant alleles influence the genome-wide somatic mutation burden in melanoma." (PMID 27403562, 2016). "Melanoma risk is increased in patients with mutations of melanocortin 1 receptor (MC1R) yet the basis for the increased risk remains unknown." (PMID 27028866, 2016). "A variant in MC1R (NM_002386.3:c.425G > A, p.R142H) has also been predicted to be likely pathogenic, was observed in Mother, Son and Daughter, and has been reported to be associated with increased risk of developing melanoma." (PMID 26547235, 2015). "However, MC1R was significantly associated with anatomic site of melanoma (p = 0.002) and a positive association was observed between carriage of more than one [R] variant and melanomas arising on the arms (OR = 2.39; 95% CI: 1.40, 4.09)." (PMID 25790105, 2015). "In addition, some alterations in genes known to be related to melanin synthesis, such as MC1R, have been reported as low-risk variants for melanoma development." (PMID 26106605, 2015). "The MC1R gene encodes melanocortin 1 receptor which is involved in the regulation of melanin pigment synthesis which has also been found to increase the risk of developing melanoma." (PMID 25945350, 2015). "A similar behavior has been shown for many natural MC1R variant alleles associated with the red hair color phenotype, with increased skin cancer risk, higher mean survival of patients and the anatomic site presentation of melanomas." (PMID 26657157, 2015). "Two exceptions to this may be the RUNX1 mutation in an individual with myelodysplastic disorder and the MC1R mutation in an individual with two melanomas." (PMID 26257771, 2015). "We examined associations between MC1R variants and histopathological melanoma characteristics." (PMID 25790105, 2015). "We did attempt to draw a comparison between our results and results from a case-control study of sporadic and familial melanoma in a Swedish population, which reported an increased association between carriage of ≥1 MC1R variant and melanoma presentation on the trunk (OR = 1.54; 95% CI: 1.01, 2.37)." (PMID 25790105, 2015). "However, our adjusted analyses revealed a strong association between carriage of more than one MC1R [R] variant and melanoma development on the arms (OR = 2.39; 95% CI: 1.40, 4.09) when compared to individuals who developed melanomas on the trunk or pelvis." (PMID 25790105, 2015). "In addition, we defined the role of rare MC1R variants and proposed a novel class of D variants that are strong melanoma risk factors." (PMID 24982914, 2014). "To determine the utility of including MC1R genotype and environmental exposure measures (outdoor and indoor UV) in melanoma risk prediction, we first developed a model based on well-established patient phenotypic factors and age (Model A), which produced an AUC of 0.72 (95% CI 0.69–0.74)." (PMID 25003831, 2014). "Our primary objective of this study, therefore, was to determine if adding a genetic marker (e.g. MC1R genotype) and indoor UV exposure measures to a clinically-based melanoma risk assessment model could improve its predictive ability." (PMID 25003831, 2014).